RBFOX3 (RNA binding fox-1 homolog 3)
Diseases named in the same sentence as RBFOX3 in open-access papers:
RBFOX3 is named in the same sentence as 200 diseases in open-access papers, as found by Europe PMC text mining. Sharing a sentence is not in itself a finding about the gene and the disease. The quoted sentences say what the papers report.
Stroke (167 papers, 2008 to 2026). Sudden impairment of blood flow to a part of the brain due to occlusion or rupture of an artery to the brain. "We observed a remarkable reduction in MAP2, RBFOX3, and GAP43 levels in the ET-1 group (all p < 0.01), suggesting a severe axonal injury occurred after stroke." (PMID 39697542, 2024).
Cognitive impairment (36 papers, 2014 to 2026). Abnormal cognition is characterized by deficits in thinking, reasoning, or remembering. "Mutations in NeuN/Rbfox3 are implicated in neurodevelopmental delay, cognitive impairments, symptoms indicative of autism spectrum disorder, and seizures." (PMID 35250487, 2022). "Dysfunction of RBFOX3 has been identified in neurodevelopmental disorders such as autism spectrum disorder, cognitive impairments and epilepsy and a causal relationship with these diseases has been previously demonstrated with Rbfox3 homozygous knockout mice." (PMID 27701470, 2016). "Our study in Rbfox3−/− mice provides an explanation for the causes of epilepsy and cognitive impairments that result from RBFOX3/NeuN mutations." (PMID 26619789, 2015). "RBFOX3 mutations are linked to epilepsy and cognitive impairments, but the underlying pathophysiology of these disorders is poorly understood." (PMID 26619789, 2015). "Moreover, RBFOX3 mutations are linked to epilepsy and cognitive impairments, while RBFOX3 knockout mice have a higher risk of developing seizures and anxiety-related behavior disorders." (PMID 37383228, 2023). "RBFOX3 mutations have been observed to be linked to cognitive impairments." (PMID 31370031, 2019). "In addition, RBFOX3 mutation in humans causes neurodevelopmental delay, cognitive impairments, autistic features, and epilepsy." (PMID 28126724, 2017). "Dysfunctional RBFOX3 has been identified in various neurological disorders such as epilepsy, cognitive impairments, developmental delay and autism spectrum disorder." (PMID 27701470, 2016). "Focusing on hippocampal phenotypes, we found Rbfox3 homozygous knockout mice displayed deficits in neurogenesis, which was correlated with cognitive impairments." (PMID 27701470, 2016). "In our current study, we not only detected cognitive deficits in Rbfox3-/- mice with alternate behavioral tests of learning (novel object recognition test) but also examined other behavioral phenotypes related to changes in brain structures and autistic phenotypes." (PMID 27701470, 2016). "Rbfox3 is exclusively expressed in neurons and dysfunctional RBFOX3 has been observed in various human brain disorders such as epilepsy, autism spectrum disorder, neurodevelopmental delay, and cognitive impairments." (PMID 27701470, 2016).
epilepsy (32 papers, 2013 to 2026). "RBFOX3 encodes a neuronal-specific RNA-binding protein involved in alternative splicing and has been linked to epilepsy and other neurodevelopmental conditions." (PMID 40692712, 2025). "If this turns out to be the case, and because Rbfox3 mutations are a known cause of epilepsy in infants, then this Rbfox3 nuclear depletion phenotype could illuminate a molecular mechanism for seizures or cryptic exon neuropathology in neonatal HI brain injury." (PMID 37887298, 2023). "Mutations in Rbfox3 have been reported in autism spectrum disorder (ASD), intellectual disability, and epilepsy." (PMID 39774335, 2025). "Here we used Rbfox3 homozygous knockout (Rbfox3−/−) mice as a model to study the neural role of RBFOX3 in the hippocampal dentate gyrus and its possible link to epilepsy and cognitive performance." (PMID 26619789, 2015).
glioma (13 papers, 2012 to 2025). A benign or malignant brain and spinal cord tumor that arises from glial cells (astrocytes, oligodendrocytes, ependymal cells). "The level of expression glioma-characteristic genes (e.g. CD34, GFAP, OLIG2, MAP2, MKI67, RBFOX3, SOX2, SYN; Suppl." (PMID 34545083, 2021).
Anxiety (12 papers, 2015 to 2025). Intense feelings of nervousness, tension, or panic often arise in response to interpersonal stresses. "We found that Rbfox3−/− mice showed increased seizure susceptibility and a reduction in anxiety-related behaviors compared with their wild-type counterparts." (PMID 26619789, 2015). "We found that Rbfox3 knockout mice displayed increased seizure susceptibility and decreased anxiety-related behaviors." (PMID 26619789, 2015). "To determine if genetic deletion of Rbfox3 in mice could recapitulate features of RBFOX3-linked human neurological disorders, we examined seizure susceptibility, cognitive function and anxiety-related behaviors in Rbfox3−/− mice." (PMID 26619789, 2015). "The circuitry for fear and anxiety is associated with the amygdala, and although not significant, the observation of a trend toward a decreased volume in the amygdala is consistent with the anxiety behavior in Rbfox3-/- mice." (PMID 27701470, 2016). "Second, Rbfox3−/− mice buried fewer marbles during the marble-burying test, suggesting these mice exhibited less anxiety-like behavior." (PMID 26619789, 2015). "To have a complete assessment of the role of RBFOX3 in DG related anxiety behaviors, we performed a battery of additional established behavioral tests on the Rbfox3−/− mice." (PMID 26619789, 2015). "Collectively, these data indicate that Rbfox3−/− mice exhibit reduced anxiety, similar to individuals with disrupted RBFOX3 in human disorders." (PMID 26619789, 2015).
autism spectrum disorder (6 papers, 2016 to 2026). A spectrum of developmental disorders that includes autism, and Asperger syndrome. "The observation of cold hyperalgesia in Rbfox3-/- mice is indicative of a sensory abnormality, similar to abnormalities of pain experienced by persons with autism spectrum disorder." (PMID 27701470, 2016). "Deletion of RBFOX3 was observed in persons with autism spectrum disorder." (PMID 27701470, 2016).
lung carcinoma (5 papers, 2013 to 2024). "We have shown for the first time that paclitaxel upregulates circIGF1R in lung cancer cells by inducing RBFOX3 and downregulates IGF1R mRNA." (PMID 38191906, 2024). "In addition, cycloheximide treatment of human lung cancer cells revealed that RBFOX3 increases the stability of Claudin-1 through attenuation of its ubiquitination." (PMID 28126724, 2017).
developmental delay (3 papers, 2016 to 2023). "Mutations in the Rbfox3 gene have been identified in patients with neonatal epilepsy, developmental delay, and language/speech disorders." (PMID 37887298, 2023).
alcohol dependence (2 papers, 2018 to 2021). Physical and psychological dependence on alcohol. "The effect of alcoholism was not sensitive to (i) changes in cell composition assessed using neuronal marker NeuN (RBFOX3) or neuronal proportion, and to (ii) smoking status." (PMID 29925858, 2018). "The effect of alcoholism × genotype interaction was not sensitive to changes in cell composition assessed using neuronal marker NeuN (RBFOX3) (−0.148 [−0.289, −0.0002], P = 0.044)." (PMID 29925858, 2018).
gastric cancer (2 papers, 2021). A primary or metastatic malignant neoplasm involving the stomach. "Luo discovers that RBFOX3 promotes cell division and invasion, and improves migratory ability in gastric cancer." (PMID 33995635, 2021).
glioneuronal tumors (2 papers, 2021 to 2025). "Looking in a supervised way at expression of particular differentiation markers commonly used for immunohistochemical analysis of glial/glioneuronal tumors, we found low GFAP expression, and modest levels of OLIG2, NeuN (RBFOX3), MAP2 and synaptophysin (SYP)." (PMID 34417833, 2021).
Rolandic epilepsy (2 papers, 2013 to 2019). "In this study, we explored if structural microdeletions and exonic sequence variations in RBFOX1, RBFOX2, RBFOX3 confer susceptibility to rolandic epilepsy (RE), a common idiopathic focal childhood epilepsy." (PMID 24039908, 2013). "Similarly, the RBFOX3 gene has been associated with neuronal differentiation as well as neurological disorders like Rolandic epilepsy and sleep latency." (PMID 31569353, 2019).
cervical cancer (1 paper, 2021). A primary or metastatic malignant neoplasm involving the cervix. "The result shows that POLR2J2, RBFOX3, RBMS1, ADARB1, AFF3, CSDC2 and CTIF were down-regulated in most of cervical cancer tissues compared with corresponding normal cervix tissues." (PMID 34863153, 2021).
cryptorchidism (1 paper, 2018). The failure of one or both testes of a male fetus to descend from the abdomen into the scrotum during the late part of pregnancy. "Recently, we compared GWAS data from non-syndromic cryptorchidism cases vs. controls and from men with TGCT with or without a history of cryptorchidism vs. controls, and discovered suggestive signals in 19 genes, including RBFOX1 and RBFOX3, paralogs that encode RNA-binding proteins (RBPs)." (PMID 30083133, 2018).
hyperuricemia (1 paper, 2015). An abnormally high level of uric acid. "A metabolic outcome of RBFOX3 knockout in mice (international mouse phenotyping consortium) is decreased circulating alkaline phosphatase, human levels of which correlates with BMI and metabolic syndrome, a component of which is hyperuricemia." (PMID 25811787, 2015).
lung adenocarcinoma (1 paper, 2017). A carcinoma that arises from the lung and is characterized by the presence of malignant glandular epithelial cells. "Our observation that protein level of Claudin-1 was decreased in RBFOX3-depleted A549 human lung adenocarcinoma cells prompted us to ask whether expression of RBFOX3 correlates with that of CLDN1 in human lung tissue." (PMID 28126724, 2017).
neuroendocrine carcinoma (1 paper, 2017). A malignant neuroendocrine neoplasm composed of cells containing secretory granules that stain positive for NSE and chromogranin. "Although RBFOX3 is detected in the cytoplasm of NSCLC or neuroendocrine carcinoma cells, the molecular function of cytoplasmic RBFOX3 is not studied yet." (PMID 28126724, 2017).
ovarian carcinoma (1 paper, 2024). A malignant neoplasm originating from the surface ovarian epithelium. "WFDC2 and KRT19 have previously been associated with ovarian cancer but RBFOX3 has not previously been identified as a potential biomarker." (PMID 39068297, 2024). "The role of RBFOX3 in ovarian cancer is, however, not well understood and we have not found any previous relating literature linking to ovarian cancer." (PMID 39068297, 2024).
tumor (108 papers, 2007 to 2025). "After induction with LPS, tumor cells highly express the transcription factor Rbfox3 and transcriptionally repress argininosuccinate synthase 1 (Ass1) expression in a phase‐separated manner, promoting the transformation of tumor cells into MLTCs." (PMID 39777898, 2025). "Over‐expression of Rbfox3 resulted in a substantial increase in tumor volume, almost doubling compared to that in the control group, and a significant decrease in the survival score of the mice." (PMID 39777898, 2025). "Crocin can inhibit the generation of MLTCs by disrupting phase‐separated particles of Rbfox3 and enhance the anti‐tumor effects of immune checkpoint inhibitors (ICIs)." (PMID 39777898, 2025). "We established an O.E. Rbfox3‐B16 cells tumor‐bearing mice model, and immunohistochemical staining of O.E. Rbfox3 tumor tissues revealed suppressed Ass1 expression in tumors with high Rbfox3 expression." (PMID 39777898, 2025). "Rbfox3 over‐expression combined with LPS stimulation (Rbfox3/LPS) B16‐EGFP tumor‐bearing model was used to evaluate the effect of Rbfox3 on MLTCs." (PMID 39777898, 2025). "At the molecular level, paclitaxel upregulated the RBFOX3 protein and circIGF1R in the tumor tissues, and downregulated IGF1R mRNA." (PMID 38191906, 2024). "Normal B16 cells and over‐expressing Rbfox3 groups were subjected to cut and run experiments to further explore the molecular mechanism by which MLTCs exert immunosuppressive effects and promote tumor development." (PMID 39777898, 2025). "Furthermore, in the MNA tumours, RBFOX3 was upregulated, whereas RBFOX1 was downregulated, perhaps indicating changes in splicing." (PMID 32707690, 2020). "Among the genes involved in the mRNA binding, RBFOX3 is also a regulator in the process from pri-miRNA to pre-miRNA and could promote tumor growth and progression via hTERT signaling in the HCC." (PMID 32219019, 2020). "Multivariate modelling, including all proteins independent of their association in the univariate analysis, identified a model for separating benign conditions from malign tumours (stage I–IV) consisting of three proteins; WFDC2, KRT19 and RBFOX3." (PMID 39068297, 2024). "Meanwhile, Rbfox3 and SFRTM2 levels were downregulated while the levels of the fibrosis markers HGF, HMOX1, ELN, and GREM1 were upregulated in the tumor microenvironment of NEPC." (PMID 37240308, 2023). "We note that the RBFOX family of proteins includes RBFOX1, RBFOX2, and RBFOX3; however, RBFOX1 and RBFOX3 show the greatest extent of downregulation across different tumours (>60-fold), whereas RBFOX2 shows comparatively moderate downregulation (~3-fold)." (PMID 35987939, 2022). "We tested this hypothesis by establishing a B16‐EGFP tumor‐bearing model using normal B16‐EGFP cells, Rbfox3 knockout B16‐EGFP cells, or Nbr1 knockout B16‐EGFP cells." (PMID 39777898, 2025). "In conclusion, circIGF1R acts a tumor suppressor in NSCLC by inhibiting the Wnt pathway through the VANGL2/miR-1270 axis, RBFOX3 promotes circIGF1R biogenesis by binding to IGF1R pre-mRNA, and is induced by paclitaxel to inhibit the migration and invasion of NSCLC cells." (PMID 38191906, 2024). "In the present case, the elevated expression of RBFOX3 in TME-ARPCs and the depletion of RBFOX3 in TME-de novo NEPCs may reflect the tumor progression potential of de novo NEPCs." (PMID 37240308, 2023). "For example, compared to non-tumor tissue, TRIM71 is upregulated and RBFOX3 is downregulated in tumor tissue." (PMID 33854615, 2021). "Next, we uncovered the spatial localization of the Invasive margin, through inference of copy number variations (CNVs), where the cellular tumor (CT) region was characterized by a gain of chromosome 7 and adjacent non-tumor (NT) region was delineated by high expression of RBFOX3 (NeuN)." (PMID 37434262, 2023).
infection (76 papers, 2007 to 2026). The state of being infected such as from the introduction of a foreign agent such as serum, vaccine, antigenic substance or organism. "However, synaptic depletion and neuronal loss were more pronounced, with significant reductions in Syn1 and Rbfox3 signals detected from 140 days post infection onward." (PMID 40307956, 2025). "We next investigated the kinetics of RNA levels of selected markers for neural progenitors (NES for nestin) and for markers of mature neurons (TUBB3 and RBFOX3 for β3-tubulin and NeuN, respectively) at 24 h, day 3 and 5 after infection, detected by quantitative RT-PCR." (PMID 33490061, 2020).
cancer (16 papers, 2011 to 2025). A tumor composed of atypical neoplastic, often pleomorphic cells that invade other tissues. "We noticed a subset of mRNAs that are consistently destabilized across the same cancers in which either RBFOX1 or RBFOX3 is downregulated." (PMID 35987939, 2022). "Among the RBPs we analysed, two RBPs, namely RBFOX1 and RBFOX3, stand out as being consistently deregulated across several cancer types." (PMID 35987939, 2022). "However, their effect is not limited to GBM, especially for RBFOX3, which shows a broader range of expression in normal tissues and is also downregulated in a greater number of cancers." (PMID 35987939, 2022). "While RBFOX3, RBM11 (RNA binding motif protein 11) and DDX25 (DEAD-box helicase 25) are generally downregulated in cancers compared to normal cells, the dysregulation of CELF5, ELAVL2 and ESRP1 is dependant on the type of cancer." (PMID 30704403, 2019).
neurological disorders (5 papers, 2015 to 2023). "To address the potential causal role of RBFOX3 in neurological disorders, we first generated Rbfox3 homozygous knockout (Rbfox3−/−) mice carrying a knockout-first and conditional-ready allele of the Rbfox3 gene." (PMID 26619789, 2015). "Future studies are needed to identify the precise presynaptic and postsynaptic proteins that are regulated by RBFOX3, as these may serve as targets for therapies of RBFOX3-linked neurological disorders." (PMID 26619789, 2015). "Despite its expression in almost all mature neurons and its relevance to human neurological disorders, little is known about the physiological role of RBFOX3." (PMID 26619789, 2015).
brain disorder (3 papers, 2015 to 2018). A disease affecting the brain or part of the brain. "The Rbfox3-/- mouse model is important for studying human brain disorders associated with dysfunctional RBFOX3." (PMID 29401485, 2018). "How exactly RBFOX3 causes its related brain disorders remains unclear and the role of RBFOX3 in the brain is largely unknown." (PMID 27701470, 2016). "Our findings may offer mechanistic explanations for human brain diseases associated with dysfunctional RBFOX3." (PMID 27701470, 2016). "Our findings indicate the potential contributions of RBFOX3 to the pathogenesis of brain diseases with disrupted RBFOX3." (PMID 27701470, 2016). "Together, our results demonstrate anatomical and functional abnormality in Rbfox3 knockout mice, and may provide mechanistic insights for RBFOX3-related human brain disorders." (PMID 26619789, 2015). "Importantly, our study results indicate that the key features of RBFOX3-related human brain disorders are recapitulated in Rbfox3−/− mice, and that this mutant mouse can be a powerful model for understanding relevant human neuropsychiatric disorders." (PMID 26619789, 2015).
neurodevelopmental disorder (3 papers, 2016 to 2023). A behavioral and cognitive disorder with onset during the developmental period that involves impaired or aberrant development of intellectual, motor, or social functions. "It remains to be clarified if RBFOX3 and RBFOX2 are involved in the establishment of cortical architecture and neurodevelopmental disorders including ASD." (PMID 27481563, 2016).
RBFOX3 also shares sentences with these, for which no sentence is quoted: ischemia (86 papers); Cerebral ischemia (69); ischemic stroke (38); depression (16); schizophrenia (14); diabetes (13); cerebral infarction (12); Hyperglycemia (11); viral infection (10); breast carcinoma (9); hematoma (9); memory impairment (9); status epilepticus (9); Alzheimer disease (8); tauopathy (8); amyloid (7); infarction (7); neuroblastoma (7); neurodegenerative disease (7); ZIKV infection (6); injury (5); Parkinson disease (5); astrocytoma (4); bipolar disorder (4); hippocampal atrophy (4); neurocytomas (4); Neurodevelopmental delay (4); prion disease (4); Sepsis (4); brain injuries (3).
A further 146 diseases each share a sentence with RBFOX3 in 3 papers or fewer.